NOTCH2 (notch receptor 2)
Diseases named in the same sentence as NOTCH2 in open-access papers (continued):
Sharing a sentence is not in itself a finding about the gene and the disease.
cancer (201 papers, 2008 to 2025). A tumor composed of atypical neoplastic, often pleomorphic cells that invade other tissues. "Dysregulation of the NOTCH signaling is implicated in the pathogenesis of many cancers, yet the specific role of NOTCH2 in solid tumors remains controversial." (PMID 41200204, 2025). "NOTCH2 is associated with cancers and female genital system diseases according to the databases; therefore, the NOTCH2 gene was selected for the following experiments." (PMID 37728427, 2023). "In the present study, the NOTCH2 P2113S mutation triggered malignancy by promoting cancer cells’ ability to migrate, invade, and proliferate." (PMID 37728427, 2023). "In total, 22% of primary EBV + DLBCLs (10/46) harbored mutations affecting NOTCH1 or NOTCH2. dNdScv confirmed both genes as significant cancer driver genes." (PMID 36604606, 2023). "We found significant differences in mutation frequencies of NOTCH1 and NOTCH2, copy number variations (CNVs) at both gene and chromosomal arm levels, and cancer-related HIPPO, WNT, and NRF2 signaling pathways between ESCC tumors and normal mucosa." (PMID 35515115, 2022). "A wide range of cancer types have been found to overexpress Notch2 or to exhibit Notch2 gain-of-function mutations." (PMID 34440225, 2021). "In this setting, a genome-wide approach revealed a rarer copy number increase of the mutated Notch 2 allele, a phenomenon previously associated with oncogenic gene alterations in other cancers." (PMID 33374160, 2020). "Available reports evident that, majority of cancers especially B-cell malignancies have also been associated with overexpression of Notch2 or Notch2 gain-of-function mutations that enhances Notch2 activity, causing tumorigenesis." (PMID 33400727, 2020). "Emerging reports have established the oncogenic role of Notch2 signaling and its deregulation have been implicated in variety of cancers which makes Notch2 an excellent candidate for investigation." (PMID 33400727, 2020). "It is important to point out that this is the first time that STAT2, NFE2L1, SIN3B and NOTCH2 genes are described associated to the cancer stroma." (PMID 31159827, 2019). "Rare and possibly damaging variants were identified in 12 candidate genes in this cohort, including variants in DNA repair genes (ERCC1 and SXL4) and other cancer-related genes (NOTCH2, ERBB2, MST1R, and RAF1)." (PMID 29868112, 2018). "We selected those genes with functions known to be associated with cancer of which there were 12—SNVs: NOTCH2, PIK3CG, IL2RB, BAI3, FREM2 and RERE; indels: UTRN, CDHR3, NCOA5, CABYR, HOTAIR and FOLH1." (PMID 26017033, 2015). "Further, the Notch pathway is an important driver in oncogenesis, as activating mutations in Notch pathway components, such as NOTCH1 and NOTCH2, can drive specific cancer types." (PMID 24874471, 2014). "Among the numerous possible candidates, we picked out the ones overexpressed in cancers and proliferation- and metastasis-associated genes, including NOTCH2, FGFR1, CSF1, AGAP2, CREB1, for further analysis." (PMID 24614175, 2014). "Functional enrichment analysis further supported the oncogenic role of NOTCH2, revealing significant associations between its high expression and hallmark signaling pathways implicated in cancer progression, including the PI3K-AKT, TGF-β, MAPK, mTOR, and KEAP1-NFE2L2 signaling." (PMID 41200204, 2025). "Compared with the low-NOTCH2 group, patients with high NOTCH2 expression exhibited a significantly higher proportion of M2 macrophages, a subtype associated with immunosuppressive phenotypes and malignant tumor progression." (PMID 41200204, 2025). "NOTCH2 expression was found to be significantly associated with poor prognosis in several cancers." (PMID 41200204, 2025). "NOTCH2 gain-of-function (GOF) forms, i.e., variants that enhance NOTCH2 activity, are tumorigenic by rendering transformed cells into a less-differentiated immortalized state, thereby facilitating the stem cell-like proliferation of cancer cells." (PMID 39684291, 2024).
cancer (continued). "Consistently, this study identified NOTCH2 mutations in 26.67% (20 of 75) of the cancer cases." (PMID 37728427, 2023). "In light of the observation that GSI are less effective in clinical studies, we hypothesize that GSI resistance might be a widespread characteristic of NOTCH2 associated human malignancies." (PMID 28736522, 2017). "NOTCH2 encodes a receptor of the Notch family, of which the members have temporally regulated function and expression in the development and maintenance of the normal mammary morphology and influence several hallmark genes in a cancer-specific manner, including in BC." (PMID 39696035, 2024). "In addition, Notch2 expression is positively associated with cancer recurrence rate." (PMID 34485133, 2021). "The enhanced expression of Notch1, Notch2, and Nanog in salispheres and ALDHhighCD44high cells suggests the function of cancer stem cells in ACC." (PMID 40371051, 2025). "While the downregulated DEGs in the Control vs. Poly I: C treated group of Gaddi dogs showed pathways highlighting, such as in cancer with NOTCH2, MDM2, and E2F3, the pathway related to RNA metabolism was also enriched for genes such as HNRNPA3 and XPO1." (PMID 40621499, 2025). "Of particular note is a small core of microRNA-regulated proteins, which also represent important nodes in altered functions in cancer, including ErbB2, NFkB1, and Notch2." (PMID 40004024, 2025). "Dll4 was expressed in cancer cells and engaged Notch1 signalling in an autocrine way, whereas Jag1 was expressed in neighbouring hepatic stellate cells and engaged Notch2 signalling in neighbouring cancer cells." (PMID 40052152, 2025). "The “Low Mappability” list impacted six cancer drivers, including NOTCH2 and SSX2 (SSX family member 2)." (PMID 39975128, 2025). "To examine the relationship between NOTCH2 expression and immune infiltration, we employed a comprehensive pan-cancer analysis using the ESTIMATE, CIBERSORT, and ssGSEA algorithms." (PMID 41200204, 2025). "The top cancer genes with recurrent variants included: STAT2 (33%), DMNT1 (27%), HSP90AA1 (17%), CDK4, NOTCH2, THRAP3, and SALL4 (13% each)." (PMID 41353477, 2025). "In HNSC, both expression and DEG enrichment of JAG1, DLL1, and NOTCH2 significantly increased after anti-cancer therapy, while DLL3 and NOTCH4 significantly decreased." (PMID 39074091, 2024). "Epigallocatechin-3-gallate (EGCG), the main polyphenol in green tea, decreased the expression of Notch receptors including Notch1 and Notch2 in several cancer models." (PMID 39092224, 2024). "This fibroblast phenotype is induced by direct contact with cancer cells and is mediated by Jagged1 in cancer cells and Notch2 in fibroblasts." (PMID 38730588, 2024). "Combining WES data and TDS data, 75 specimens were evaluated (11 samples in WES and 64 samples in TDS); NOTCH2 mutations were determined in 20 samples (1 in the WES analysis and 19 in the TDS analysis) with a rate of 26.67 % (20 of 75) among cancer cases." (PMID 37728427, 2023). "Regarding Notch receptors, NICD1 was strongly expressed in the nuclei of cancer cells present in area #1, while the expression of Notch2 intracellular domain (NICD2) was rather weak." (PMID 35064244, 2022). "Gene expression analysis showed that epithelial cells in type 3 TETs expressed high levels of cancer stem cell (CSC)-related markers (NOTCH2, CD24, ALDH1B1 and PROM1)." (PMID 36115836, 2022).
cancer (continued). "Mutations in cancer-related genes (KMT2C, NOTCH2, PRKAR1A, SDHA, and USP6) and genes related to EC (ARID1A, CTNNB1, PIK3CA, and PTEN) were identified with high frequencies among the three samples." (PMID 35626111, 2022). "Dll4 is expressed in cancer cells and activates Notch1 signaling in an autocrine manner, while Jag1 is expressed in the neighboring HSCs and activates Notch2 signaling in adjacent cancer cells." (PMID 35064244, 2022). "Eckol suppressed expression of Notch2 and β-catenin in the cancer stem-like cells in several human cancers." (PMID 34440090, 2021). "Compared with adjacent tissues, AGAP2-AS1 and NOTCH2 expression were elevated while miR-296 expression was reduced in cancer tissues." (PMID 33972506, 2021). "Since activation of PI3K/AKT pathway is known to promote cell proliferation, cell survival, growth and angiogenesis in cancers, it is important to know if Notch2 propels cancer progression through activation of this pathway." (PMID 33400727, 2020). "Four cancer‐driver genes NOTCH2, ASXL1, PDE4DIP, and MUC4 were found to be selectively amplified in both hESC‐RPE and HS980 (p38) samples." (PMID 32319201, 2020). "Tarextumab, a fully human antibody that targets cancer stem cells through inhibiting Notch 2 and 3 receptors, was evaluated in a randomized phase 2 trial of 177 patients with metastatic pancreatic adenocarcinoma." (PMID 31338636, 2020). "Blocking antibodies against Dll4, Notch1, Notch2, or Notch3 are already being tested in phase I clinical trials in cancer patients." (PMID 31191522, 2019). "The results of ChIP-seq showed that YB-1 maintained the stemness of cancer stem cells by promoting the expressions of stemness-associated genes (FZD-1, p21, GLP-1, GINS1, and Notch2)." (PMID 31375149, 2019). "CircNotch2 derived from Notch2, an important therapeutic target in cancer treatment, was also expressed in all the lineages." (PMID 31446897, 2019). "Her2 overexpression is associated with an increased subpopulation of cancer stem cells and correlates with activation of the PI3K/AKT pathway, leading to increased expression of stem cell markers Oct3/4, Notch1, Notch2, Jagged1 and Gli1." (PMID 31608299, 2019). "The results revealed that YB-1 knockout led to significant decreases in the promoter activities of the FZD-1, p21, GLP-1, GINS1, and Notch2 genes in cancer stem cells." (PMID 31375149, 2019). "For example, Notch2, the key gene in the notch signaling pathway, has had circRNAs identified in 349 (37.3%) cancer cell lines." (PMID 31446897, 2019). "NOTCH2 was slightly upregulated in three of the analyzed cancer cell lines as compared to control, while NOTCH3 and NOTCH4 were variable and low expressed in PTC cell lines TPC1 and BCPAP." (PMID 30158530, 2018). "It is also of note that loss of “site-associated” genes such as WRN, NOTCH2, MBD1 and PI3KR1 had already been associated to development of human cancer." (PMID 29755661, 2018). "Of those, we highlight four genes related to cancer development and progression (NOTCH2, ERBB2, MST1R, and RAF1) and two DNA repair genes (ERCC1 and SLX4)." (PMID 29868112, 2018). "Here, we identified Notch2 signal as a key factor in maintaining canine HSA cancer stem cell (CSC)-like cells." (PMID 30285832, 2018). "By suppressing Notch2 signalling, c8orf4 negatively regulates the self-renewal of cancer stem cells in the liver." (PMID 30470250, 2018). "The NOTCH2 gene is involved in the direct cell-cell interactions of the Notch pathway that can inhibit cancer progression." (PMID 30102725, 2018). "Given that NOTCH2, FBXW7 and DLL1 are key components in NOTCH signaling and have predictive value in cancer therapies, the effect of these mutations in NPC is yet to be elucidated." (PMID 28256603, 2017). "Our results are in line with recent findings showing that Notch2 signaling controls proliferation of various stem cell populations (e.g., bone marrow stem cells) and cancer cells." (PMID 28611689, 2017).
cancer (continued). "In both subgroups, there are rare cancer-promoting mutations predicted to activate the PI3K pathway (HRAS, KRAS, PIK3CA, PTEN, and TSC1) and to inactivate the Notch pathway (Notch1 and Notch2)." (PMID 26655088, 2016). "In the present study, log-rank and multivariate analyses demonstrated that Notch2 expression in cancer tissues served as an independent prognostic factor for OS and PFS in ESCC patients." (PMID 27158037, 2016). "Gene expression microarray data demonstrated that Notch2 is one of the most upregulated genes in a cancer stem cell-like population." (PMID 26464794, 2015). "We found that prostate benign cells generally have higher baseline Notch1 and Notch2 expression and more Notch pathway activation than cancer cells." (PMID 25864518, 2015). "This approach identified candidate variants in known cancer genes, including in BCOR, NOTCH2, TET2, NF1, EZH2, and JAK1." (PMID 28721364, 2015). "NOTCH2 is overexpressed in multiple cancer types and has been shown to have oncogenic effects, including on proliferation." (PMID 25992613, 2015). "Specifically, benign prostate cells had the highest levels of Notch1 protein and higher levels of Notch2 protein than three of four cancer lines." (PMID 25864518, 2015). "Collectively, these findings suggest divergent functions of NOTCH1 and NOTCH2 in UC, which have also been observed in other cancers." (PMID 25167871, 2014). "ARID3B induced expression of genes associated with metastasis and cancer stem cells (CD44, LGR5, PROM1 (CD133), and Notch2)." (PMID 25327563, 2014). "Immunoblot analyses also showed that the expression of “cancer stemness” proteins (Oct-4, Nanog and Notch2) and GRP78 was diminished in YMGKI-1-treated SAS-HN-CICs." (PMID 23843890, 2013). "Although various results were generated by deFuse and TopHat-Fusion, a fusion event between PTGFRN and NOTCH2 was the only cancer-specific fusion event identified by both algorithms." (PMID 22905095, 2012). "Furthermore, MDK is known to activate Notch2 signaling in cancer cells, leading to epithelial-mesenchymal transition (EMT), drug resistance, and aggressive tumor behavior." (PMID 40500394, 2025). "Role of circRNAs in the regulation of NOTCH 2 expression in cancers." (PMID 40761890, 2025). "To delve deeper into the MFAP5-regulated signaling pathway, we conducted a literature review and found that MFAP5 might activate the Notch2 and or HEY1 in other cancer type and Notch2 has been recognized as an oncogene that enhances invasion in GC." (PMID 39524442, 2024). "In cancers, NUP54 induces nuclear import of coactivator-associated arginine methyltransferase 1 (CARM1) and, consequently, transcriptional activation and neurogenic locus notch homolog protein 2 (Notch2) methylation, thereby accelerating GC cell proliferation and tumorigenesis." (PMID 39080077, 2024). "In particular, NOTCH2 H107P and BCR T1127S variants were almost clonal (i.e., present in all somatic cells), whereas EPHA7 L564F and MTOR S920F were subclonal alterations, present in around 35% of cancer cells." (PMID 39421445, 2024). "USP8 and NOTCH2 are well-known oncogenes that are frequently overexpressed in human cancers." (PMID 39456581, 2024). "Both USP8 and NOTCH2 are frequently overexpressed in human cancers." (PMID 39456581, 2024). "Mutations in Notch2 are linked to Hajdu–Cheney syndrome, Alagille syndrome 2 (ALGS2), and cancer." (PMID 38790158, 2024). "DTX3 is an E3 ligase that targets NOTCH2 and activates proliferation in cancer." (PMID 36790929, 2023). "Considering the roles of Notch2 antagonism in preserving bone homeostasis along with anti-cancer activity of Notch inhibitors, it is reasonable that targeting Notch2 can be considered as a potential treatment regimen against malignancies and also protecting bone." (PMID 35563828, 2022).
cancer (continued). "Studies have corroborated that miR-195-5p, down-regulated in CRC tissues and related to poor prognosis in CRC sufferers, modulates the notch receptor 2 (NOTCH2)-mediated epithelial-mesenchymal transformation to influence M2-like macrophage polarization in the cancer." (PMID 35014946, 2022). "Expression of other target genes ITGA5 and NOTCH2 could improve the stemness and metastatic potential of hematogenously disseminated cancer cells." (PMID 35008529, 2021). "Interestingly, tarextumab was found to inhibit Notch 2/3 activity and Notch target gene expression in both human-derived cancer cells and the mouse-derived stromal cells in the xenografts, suggesting an interaction with multiple cell types." (PMID 32575680, 2020). "NOTCH2 expression was notably concentrated at the interface between the malignant epithelium and the stroma, and it lined the whole extension of the cancers observed." (PMID 32155948, 2020). "In addition, MDK also has been linked to cancer cell invasion and metastasis via epithelial-mesenchymal transition (EMT) which has three major pathways: WNT signaling, TGF-β signaling, and Notch2 signaling pathways." (PMID 32847073, 2020). "Nevertheless, establishing the role of PI3K/AKT pathway in Notch2 activated cancers could be very important to consider it as an alternative treatment target in mitigating the effects of Notch2 transactivity in these cancers." (PMID 33400727, 2020). "However, rescue of YB-1 expression resulted in significant increases in the promoter activities of the FZD-1, p21, GLP-1, GINS1, and Notch2 genes in YB-1 knockout cancer stem cells." (PMID 31375149, 2019). "NOTCH2 is regarded as an oncogene, and plays an essential role in cancer signaling pathways." (PMID 31160636, 2019). "Importantly, MDA-MB-231 LM and matching parental cells expressed nominal levels of NOTCH1 and NOTCH2, suggesting that LY411575-mediated inhibition of cancer cell seeding and metastatic growth was primarily linked to inhibition of the NOTCH3 signaling pathway." (PMID 30180881, 2018). "Importantly, because MDA-MB-231 LM and parental cells showed nominal levels of NOTCH1 and NOTCH2, these results suggest that LY411575-mediated inhibition of cancer cell seeding and metastatic growth was likely associated with NOTCH3 targeting." (PMID 30180881, 2018). "We hypothesized that the Tg6F-mediated increase in Notch1 and Notch 2 with increased Dll4 and Dll1 expression in the jejunum in the cancer model might affect the immune cell repertoire." (PMID 29899427, 2018). "Moreover, a previous paper implies that human TC1 blocks the entry of activated Notch2 into the nuclei of cancer stem cells." (PMID 28382040, 2017). "Additionally, IHC staining revealed that Notch2 was primarily localized to the cytoplasm of cancer cells." (PMID 27158037, 2016). "Furthermore, miR-150 directly down-regulated the expression of other cancer stem cell factors including Notch2 and CTNNB1." (PMID 27917123, 2016). "Notch2 expression was primarily localized to the cytoplasm of cancer cells." (PMID 27158037, 2016). "Notch2 has the potential to serve as a predictive biomarker in a variety of cancers." (PMID 27158037, 2016). "Similarly, compared to normal tissue, there was a slight increase in the expression levels of Notch2 in cancers." (PMID 20030805, 2009). "However, low NOTCH2 expression levels are related to poor outcomes in cancer." (PMID 33479597, 2020). "Similarly, Notch2 knockdown suppressed cancer progressions of AZ521 and AGS GC cells." (PMID 28416750, 2017). "These variants were found in over 45% of the cohort and occurred in genes with known relevance to cancer biology, including CHEK2, RAD54L, NOTCH2, ASXL1, PDGFRA, and KIT." (PMID 40627234, 2025). "Our observation that MHCII+ monocytes expand in Notch2-deficient mice in steady-state conditions might also be in line with NOD2-dependent inducible monocytes and potentially open new treatment options by modulating monocyte Notch2 signaling in cancer patients." (PMID 41244563, 2025).